MRPS23 (mitochondrial ribosomal protein S23)
Synonyms: MRP-S23; CGI-138; HSPC329; mS23; COXPD46
Tractability: Small molecule: a structure with a bound ligand is known. PROTAC: ubiquitination databases record sites on it; its protein half-life has been measured.
Target class: Other cytosolic protein
Gene: Protein-coding gene on chromosome 17 (57,834,781 to 57,850,076, reverse strand). Ensembl gene ENSG00000181610.
Subcellular location: Mitochondrion
Subcellular location (Human Protein Atlas): Mitochondria; Nuclear membrane
Pathways (Reactome):
Metabolism of proteins: Mitochondrial ribosome-associated quality control; Mitochondrial translation elongation; Mitochondrial translation initiation; Mitochondrial translation termination
Gene Ontology:
Molecular function: protein binding; RNA binding; structural constituent of ribosome
Biological process: mitochondrial translation; translation
Cellular component: mitochondrion; mitochondrial inner membrane; mitochondrial small ribosomal subunit; ribosome
Genetic constraint (gnomAD): Loss-of-function variants: 15 observed, 20.67 expected, observed/expected ratio (o/e) 0.73, 90% interval 0.48 to 1.12. The upper end of that interval is the gene's LOEUF score, 1.12, which puts it in group 4 of 6, group 1 being the genes least tolerant of losing a copy. Missense variants: 242 observed, 245.61 expected, observed/expected ratio (o/e) 0.99, 90% interval 0.89 to 1.1. Synonymous variants: 113 observed, 93.01 expected, observed/expected ratio (o/e) 1.21, 90% interval 1.04 to 1.42.
Gene-disease validity (ClinGen):
ClinGen rates the evidence that MRPS23 causes each of these diseases.
mitochondrial disease (autosomal recessive): Limited.
Homologues: Orthologues: chimpanzee MRPS23 (99% identical), macaque MRPS23 (87% identical), rabbit MRPS23 (79% identical), dog MRPS23 (79% identical), pig MRPS23 (76% identical), mouse Mrps23 (69% identical), rat Mrps23 (68% identical), guinea pig MRPS23 (65% identical), tropical clawed frog mrps23 (52% identical), zebrafish mrps23 (45% identical), Drosophila melanogaster mRpS23 (33% identical), Caenorhabditis elegans mrps-23 (26% identical).
Diseases named in the same sentence as MRPS23 in open-access papers:
MRPS23 is named in the same sentence as 39 diseases in open-access papers, as found by Europe PMC text mining. Sharing a sentence is not in itself a finding about the gene and the disease. The quoted sentences say what the papers report.
breast carcinoma (19 papers, 2017 to 2026). "The overexpression of MRPS6 and MRPS23 in breast cancer cells and tissues is associated with increased tumor cell proliferation." (PMID 40371222, 2025). "After 10 years of follow-up, cases with low MRPS23 expression levels had a cumulative risk of death from breast cancer of 26% (95% CI 23–29%), compared to 24% (95% CI 20–30%) among cases with high MRPS23 expression (Cut-off upper quartile)." (PMID 31950385, 2020). "After 10 years of follow-up, cases with MRPS23/CEP17 ratio < 2 had a cumulative risk of death from breast cancer of 30% (95% CI 27–34), whereas cases with ratio ≥ 2 had a corresponding risk of 41% (95% CI 30–58)." (PMID 31950385, 2020). "After 10 years of follow-up, patients with the MRPS23+/HER2+ subtype had a cumulative risk of death from breast cancer of 63% (95% CI 42–83)." (PMID 31950385, 2020). "Using FISH on a large cohort of breast cancer patients we found that MRPS23 amplification is associated with higher tumour cell proliferation." (PMID 31950385, 2020). "The MRPS23 gene, which is responsible for encoding a 28S subunit protein, has been found to be overexpressed in breast cancer, uterine cervical cancer, HCC, colorectal cancer and uterine leiomyoma." (PMID 32828126, 2020). "Additionally, hypermethylation of MRPS23 was associated with poor survival in breast cancer patients in a separate study, thus further supporting the suspected role of epigenetic regulation of MRPS23 in breast cancer progression." (PMID 39354291, 2024). "The aims of the present study were to describe MRPS23 copy number change in breast cancer, and to assess associations between MRPS23 copy number change and molecular subtype, proliferation and prognosis, and between MRPS23 gene expression and molecular subtype and prognosis." (PMID 31950385, 2020). "Post-translational modifications of MRPS23, particularly arginine and lysine methylation, facilitate metastatic progression in breast cancer by modulating oxidative phosphorylation pathways." (PMID 41522354, 2026). "The aberrant expression of MRPS23 is correlated with a poor prognosis in relation to many types of cancer, including breast cancer." (PMID 39859078, 2025). "MRPS23 is upregulated in various types of cancer, including breast cancer, HCC, pancreatic adenocarcinoma, and glioma." (PMID 39859078, 2025). "Two studies reported that MRPS23 knockdown in breast cancer cells suppressed proliferation, metastasis, and invasion while promoting apoptosis and increasing sensitivity to paclitaxel." (PMID 39859078, 2025). "Intriguingly, Oviya and colleagues (2021) found a breast cancer-specific MRPS23 isoform (or altered post-translational modification) that was expressed almost exclusively in breast cancer samples." (PMID 39354291, 2024). "Although both studies did not reveal an association with patient survival, altered expression levels support a potential role of MRPS23 in an aggressive breast cancer phenotype." (PMID 39354291, 2024). "Investigations in patient breast cancer samples have observed heightened MRPS23 expression in high-grade, aggressive tumour samples, as well as an increase in tumour compared to normal tissue." (PMID 39354291, 2024). "It has been confirmed that MRPS23 was involved in the regulation of breast cancer and hepatocellular carcinoma cell proliferation." (PMID 38301044, 2024). "Arginine and lysin methylation of MRPS23 promote breast cancer metastasis by regulating OXPHOS, which opens the door for new therapeutic options based on mitochondrial epigenetic regulation." (PMID 37275549, 2023). "A methylation study has revealed a unique mechanism by which arginine and lysine methylation of MRPS23 promote breast cancer metastasis by regulating OXPHOS." (PMID 35719986, 2022). "On the other hand, the reduced stability of MRPS23 by its methylation at arginine R21 has been shown to promote breast cancer metastasis through inhibiting OXPHOS subunit expression." (PMID 36119536, 2022).
breast carcinoma (continued). "MRPS23 degradation inhibited oxidative phosphorylation and increased mitochondrial reactive oxygen species (ROS) levels, consequently increasing breast cancer cell invasion and metastasis." (PMID 34440512, 2021). "In a breast cancer mouse model, MRPS23 knock-down reduced proliferation, induced apoptosis and limited angiogenesis and lymph node metastasis." (PMID 31950385, 2020). "We studied prognosis by estimating hazard ratios and cumulative incidence of death from breast cancer according to MRPS23 copy number and MRPS23 expression status." (PMID 31950385, 2020). "It demonstrated that knockdown of MRPS23 reduced breast cancer cell proliferation and induced apoptosis in vitro." (PMID 29069745, 2017). "To further study the biological function of MRPS23 in breast cancer progression in vivo, we first investigated the expression of MRPS23 in breast tumour tissues." (PMID 29069745, 2017). "MTS experiments showed that knockdown of MRPS23 inhibited breast cancer cell proliferation in vitro compared to controls." (PMID 29069745, 2017). "Further investigations into the molecular mechanisms of MRPS23 in the progression of different breast cancer cells still remain to be elucidated." (PMID 29069745, 2017). "There are several limitations to this study, including the retrospective analysis of correlation between MRPS23 and clinical prognosis in human breast cancer." (PMID 29069745, 2017). "Present genomic data sets have demonstrated that MRPS23 is upregulated in a series of cancers and it plays an essential role in breast cancer cell proliferation and cervical metastasis." (PMID 29069745, 2017). "Downregulation of MRPS23 results in inhibition of proliferation and metastasis, as well as facilitating apoptosis of breast cancer cells." (PMID 29069745, 2017). "Mitochondrial ribosomal protein S23 (MRPS23) has been shown to be involved in breast cancer cell proliferation and metastatic phenotypes of cervical cancer." (PMID 29069745, 2017). "Downregulation of MRPS23 by LV-mediated MRPS23 shRNA suppressed breast cancer metastasis shown by 18F-FDG microPET imaging." (PMID 29069745, 2017). "The results suggest that MRPS23 inhibited the metastasis properties of breast cancer through influencing of EMT." (PMID 29069745, 2017). "Similarly, overexpression of MRPS23 in breast cancer cells enhances resistance to CDK1 inhibitors, while knocking down MRPS23 using shRNA technology restores drug sensitivity." (PMID 40371222, 2025). "By modulating OXPHOS, methylation of MRPS23 increases breast cancer metastasis." (PMID 37507746, 2023). "The overexpression of MRPS6 and MRPS23 can impact the breast cancer tumorigenic process." (PMID 37507746, 2023). "Similarly, the overexpression of the MRPS6 and MRPS23 genes affected tumorigenic cellular processes in breast cancer and their knockdown decreased proliferation, expression of select mesenchymal marker and increased expression of tumor suppressor genes." (PMID 36119536, 2022). "In addition, MRPS23 has been identified as a driver of proliferation in luminal breast cancer, as supported by a series of in vitro and in vivo studies." (PMID 35719986, 2022). "Previous research has shown that both MRPL15 and MRPS23 can be selected as companion diagnostics, to decide which breast cancer patients might benefit most from clinical therapy (Sotgia, Fiorillo & Lisanti, 2017)." (PMID 34603851, 2021). "MRPS23 is recognized as a driver of proliferation in luminal breast cancer." (PMID 31950385, 2020). "Contrary to others, we found no clear associations between MRPS23 amplification and prognosis in our cohort of Norwegian breast cancer patients." (PMID 31950385, 2020).
breast carcinoma (continued). "Furthermore, we analysed MRPS23 gene expression data in 1971 primary breast cancer tumours from the METABRIC dataset." (PMID 31950385, 2020). "Amplification of MRPS23 is associated with higher proliferation and non-basal subtypes in breast cancer." (PMID 31950385, 2020). "After 10 years of follow-up, patients with MRPS23 amplified tumours had 40% (95% CI 27–56) cumulative risk of death from breast cancer, compared to 30% (95% CI 27–34) for patients without amplification." (PMID 31950385, 2020). "Using fluorescence in situ hybridization (FISH), we examined MRPS23 and centromere 17 copy number in 590 formalin-fixed, paraffin-embedded primary tumours and 144 corresponding lymph node metastases from a cohort of Norwegian breast cancer patients." (PMID 31950385, 2020). "HER2 is recognized as an important prognostic marker in breast cancer, and interaction with MRPS23 could potentially be of clinical importance." (PMID 31950385, 2020). "However, the molecular mechanism of how breast cancer cell progression is suppresed by knockdown of MRPS23 remains to be illustrated." (PMID 29069745, 2017). "In summary, we revealed for the first time the biological significance of MRPS23 in breast cancer." (PMID 29069745, 2017). "Nevertheless, the exact function of the molecule and the mechanism by which MRPS23 inhibits the proliferation and metastasis of breast cancer remain unknown." (PMID 29069745, 2017). "Furthermore, the true potential of MRPS23 to drive tumour genesis needs to be tested in transgenic mouse models of breast cancer." (PMID 29069745, 2017). "If the expression of MRPS23 was inhibited, it could disturb the mitochondrial protein synthesis, affect function of mitochondrial and impair breast cancer cell proliferation." (PMID 29069745, 2017). "To illustrate whether the decreased MRPS23 contributes to breast cancer cell proliferation and angiogenesis, we performed ki-67 and CD34 stain, respectively." (PMID 29069745, 2017). "Our findings may supports an oncosuppressive role of MRPS23 shRNA in rat breast cancer proliferation, angiogenesis and metastasis." (PMID 29069745, 2017). "Besides, shRNA targeting MRPS23 (shMRPS23) inhibited tumour proliferation and metastasis by blocking tumor angiogenesis in breast cancer xenograft rat model." (PMID 29069745, 2017). "Similarly, the phosphorylated form of MRPS23 by mitogen-activated protein kinase may be involved in the proliferation of breast cancer cells." (PMID 40371222, 2025). "Moreover, a rat breast cancer model found similar results; long-term MRPS23 depletion reduced tumour growth and metastasis and the authors suggested that MRPS23 may be involved in reversing the apoptotic pathway to assist metastatic progression." (PMID 39354291, 2024). "Therefore, previous studies reported the following findings: the abnormal expression of MRPS23 might serve as a poor prognostic factor of the tumor size in hepatocellular carcinomas, breast cancers, and cervical cancer." (PMID 34359790, 2021). "Inactivation of tumor suppressor genes such as RPS7, MRPL39, MRPS23, ME2, and NDUFB9 were diagnosed with the development of many cancer types such as colorectal cancer, gastric cancer, breast cancer, and pancreatic cancer, but loss of these genes may be responsible for the development of GBM." (PMID 31137733, 2019). "Thus, our findings suggested that MRPS23 might be a potential therapeutic target to alleviate breast cancer progression and metastasis." (PMID 29069745, 2017). "Expression levels of MRPS6, MRPS10, MRPS23, and MRPS31 are significantly elevated in breast cancer cells and tissues, and these findings have been corroborated by corresponding cell-based functional assay results." (PMID 35719986, 2022). "NOP14/MRPS23/POP1 exhibit prognostic value in colorectal cancer, while APOBEC3C/DCAF13/EIF4E3/EZR possess significance in predicting prognosis of breast cancer." (PMID 34322380, 2021).
breast carcinoma (continued). "For example, increased MRPS23 expression contributes to HCC cell proliferation and poor clinical outcome, and its gene amplification has been observed in cervical and breast cancer." (PMID 34772924, 2021). "The amplification of MRPS23 is positively correlated with high proliferation rates and the emergence of non-basal subtypes in breast cancer." (PMID 40371222, 2025). "Furthermore, the phosphorylation of MRPS23 by mitotic kinases influenced cell proliferation, migration, and enhanced sensitivity to CDK1 inhibitors in breast cancer cells." (PMID 39859078, 2025). "As low levels of MRPS23 result in breast cancer cell survival through regulating oxidative phosphorylation, PRMT7 overexpression inhibited oxidative phosphorylation and increased breast cancer cell invasion." (PMID 34440512, 2021). "In addition, although the MRPS23 influence on HCC remains unclear, there is evidence indicating that it can promote breast cancer metastasis by regulating OXPHOS with its arginine and lysine methylation, which has a significant reference value." (PMID 38960931, 2024). "There were no clear differences in the rate of death from breast cancer between the MRPS23−/HER2+ and MRPS23+ /HER2+ subtypes (HR 1.3, 95% CI 0.7–2.6)." (PMID 31950385, 2020).
colorectal cancer (5 papers, 2019 to 2026). A primary or metastatic malignant neoplasm that affects the colon or rectum. "MRPS23 has been identified as one of twelve functionally significant RNA-binding proteins demonstrating prognostic relevance in colorectal carcinoma, though intriguingly, its elevated expression correlates with improved clinical outcomes." (PMID 41522354, 2026). "MRPS23 also has prognostic value in colorectal cancer, where it was identified as one of 12 prognostic RNA binding proteins." (PMID 39354291, 2024). "Although expression was increased in colorectal cancer, and was considered prognostic, the authors considered this expression profile to be low-risk (HR = 0.589) and did not elucidate the specific function of MRPS23 in colorectal cancer progression." (PMID 39354291, 2024).
cervical carcinoma (4 papers, 2017 to 2026). A carcinoma arising from either the exocervical squamous epithelium or the endocervical glandular epithelium. "MRPS23 is also more strongly associated with metastatic phenotypes in cervical cancer." (PMID 29069745, 2017). "The oncogenic role of MRPS23 was first found in metastatic progression, with its upregulation identified in recurrent cervical carcinomas exhibiting lymph node metastasis and enhanced proliferative and invasive capacities." (PMID 41522354, 2026).